IL1A (interleukin 1 alpha)
Diseases named in the same sentence as IL1A in open-access papers (continued):
Sharing a sentence is not in itself a finding about the gene and the disease.
influenza (27 papers, 2009 to 2025). An acute viral infection of the respiratory tract, occurring in isolated cases, in epidemics, or in pandemics; it is caused by serologically different strains of viruses (influenzaviruses) designated A, B, and C, has a 3-day incubation period, and usually lasts for 3 to 10 days. "Systemic delivery of bNAbs to treat influenza infections caused the proinflammatory cytokines IL-1α and IL-1β levels to rise even higher than those seen in untreated infected animals." (PMID 32847855, 2020). "Humoral responses were further confirmed by the reduced numbers of influenza-specific IgG antibody-secreting cells (ASCs) in the LNs of mice deficient in IL-1α or the IL-1 receptor, and conversely, by the increased numbers in mice treated with IL-1α or IFN-β." (PMID 40977695, 2025). "While it is well understood that an IL-1R1-deficiency increases influenza-related mortality at time-points later than were assessed in this paper, studies are on-going to examine the outcome of IL-1α blockade to antiviral responses (later than 5 days post-infection) in smoke-exposed mice." (PMID 22163019, 2011). "There are several studies have showed that influenza patients displayed markedly increased expression of IL-1α, and the expression level positively correlate with the severity of influenza infection, as well as the elevation of platelet count." (PMID 38166827, 2024). "Lung homogenates were evaluated by multiplex ELISA (Quansys) to quantify several cytokines (TNFα, IFNγ, IL-1α, IL-1β and IL-6) and chemokines (MCP-1, MIP-1α and RANTES) implicated in influenza-mediated acute lung injury 33,34." (PMID 35410323, 2022). "Consistent with the results of our previous experiments, LS inhibited the expression of inflammatory factors such as TNF-α、IL-6、IL-1α、IFN-γ after influenza infection in vivo and in vitro." (PMID 36034844, 2022). "In a previous study, we observed that the necrotic death of the LN macrophages after the administration of influenza vaccine was followed by the release of the potent inflammatory cytokine IL-1α." (PMID 31824481, 2019). "We found an increase in the levels of the inflammatory cytokines IL-1α, IL-1β, TNFα, IL-6, IL-12p40, IL-17, and IFNγ, and increased levels of the Type 2 cytokines IL-4 and IL-5, in influenza-infected Stat2−/− mice when compared to WT mice." (PMID 30337919, 2018). "Before influenza infection (day 0, D0), we observed significantly higher levels of pro-inflammatory cytokines IL-1α and IL-1β in L. paracasei-fed mice compared to PBS-fed mice." (PMID 28931041, 2017). "L. paracasei consumption seems to allow an early activation of pro-inflammatory cytokines (IL-1α, IL-1β) and a massive recruitment of immune cells in the lungs after L. paracasei gavage and prior to influenza infection." (PMID 28931041, 2017). "Over-expression of several regulated cytokines including IL-1α, IL-1β, TNF-α, and IFN-γ have been associated with morbidities in influenza infection, and spontaneous pregnancy loss." (PMID 22792357, 2012). "Our study evaluated nasal epithelial cells differentiated from five different donors, which mounted a consistent response against influenza, with potential differential responses between individuals in antiviral response genes such as IFNλs, IL36γ, IL-1A, and ICAM-1." (PMID 30487780, 2018). "While an IL-1R1 deficiency could lessen exaggerated inflammatory responses in smoke-exposed influenza-infected animals, we hypothesized that IL-1α would play a predominate role in promoting this response." (PMID 22163019, 2011). "However, IL-1α levels were significantly enhanced in OVA-sensitized animals exposed to DEP prior to infection with influenza." (PMID 19682371, 2009). "QQXD can reduce the expression of IL-1α, IL-4, IL12(P70), and TNF-α inflammatory factors in influenza mice, and prevent the excessive inflammatory reaction from aggravating lung injury." (PMID 36313993, 2022).
influenza (continued). "In addition, our recent study demonstrated that there are lingering inflammatory cytokines such as IL-6, IL-1α, and G-CSF in the bronchiolar lavage fluid (BAL) of aged mice during influenza infection." (PMID 28979265, 2017). "They found that interleukin-1 receptor (IL-1R) deficiency led to a reduction of neutrophils following infection with influenza and that this effect was independent of IL-1α." (PMID 24918427, 2014). "However, it is interesting that the four pro-inflammatory cytokines induced by Pam2-ODN 4 h after treatment (IL-1α, IL-1β, IL-6, and TNF) are also the first four pro-inflammatory cytokines induced from respiratory epithelial cells in native influenza infections." (PMID 22299046, 2012). "No appreciable levels of IL-1β, MIP-1α or MIP-1β were detected from the basolateral or apical compartments of AIV or human influenza infected NHBE cells (data not shown); however, AIVs induced differential apical and basolateral expression patterns of IL-1a, IL-8, IP-10, MCP-1, and RANTES over time." (PMID 21731666, 2011). "CK5 also shared similar correlations with CK14 for IL-1a and IL-13 in FLU− populations; however, beyond these highlights, the expression of CK5 did not correlate with many of the cytokine expressions exhibited with other cytokeratins, regardless of influenza positivity of the cells." (PMID 39791909, 2025).
acne (26 papers, 2009 to 2025). An inflammatory process of the sebaceous glands which is characterized by comedones, nodules, papules and/or pustules on the skin. "Several studies found that the IL1A − 889 C/T SNP (rs1800587) was associated with acne among Asian and European populations while + 4845 G/T SNP only showed association among Caucasians in Hungary/Romania, but not in USA." (PMID 33849530, 2021). "First, we identified loops in promoter capture Hi-C (pc Hi-C) in keratinocytes encompassing the acne-associated variants, highlighting that both variants interact with the promoter region of IL1A, with rs2708914 also connected to IL1B, complementing the eQTL results." (PMID 39975900, 2025). "IL-1α causes keratosis of the hair follicles and sebaceous glands, causing acne." (PMID 32627753, 2020). "The ability of CBD to counteract the C. acnes-induced inflammatory response by downregulating cytokines like CXCL8, IL-1α, and IL-1β further positions it as an anti-inflammatory agent for acne." (PMID 38904694, 2024). "Treatment of keratin-forming cells with glucocorticoids can increase the expression of TLR-2 receptors and increase the release of TNF-α and IL-1α, thus playing an important role in the formation of acne." (PMID 38585341, 2024). "The high levels of IL-1α have been proven to play a role in acne development in the presence of proinflammatory cytokines." (PMID 36838382, 2023). "Pharmacologic EGFR inhibition in nonresistant CRCs is associated with compensatory FGFR2-induced p38/MAPK upregulation that induces the downstream proinflammatory mesenchymal mitogen IL-1α which in turn promotes both sporadic acne and iatrogenic folliculitis." (PMID 34007277, 2021). "The most refractory complication of acne is scar formation, which involves the production of pro-inflammatory cytokines such as IL-1α, IL-1β, IL-6, TNF-α, and TGF-β54." (PMID 32765835, 2020). "The Eucalyptus globulusand Arum palaestinum herbal extract inhibits interleukin 1 alpha with high phenolic and flavonoid content with potential anti-inflammatory and anti-acne agent for Acne vulgaris." (PMID 33187049, 2020). "It has previously been reported that sebum secretion is increased by ultraviolet (UV) radiation and that IL-1α, −1ra, − 6, and − 10 production is upregulated in acne patients." (PMID 31174532, 2019). "TLR2 bacterial ligands present on C. acnes have been proposed to promote inflammation in acne, stimulating interleukin-1alpha (IL-1α), and granulocyte macrophage-colony stimulating factor (GM-CSF) release." (PMID 30285861, 2018). "We sought to establish a link between cutaneous flora, the release of IL-1α and the acne life-cycle." (PMID 24011352, 2013). "High levels of the pro-inflammatory cytokine IL-1α were reported in acne lesions in vivo, and previous work revealed that exposure of isolated infundibula and pilosebaceous units to IL-1α in vitro induced comedone formation." (PMID 24011352, 2013). "We suggest that IL-1α release from infundibular keratinocyte in response to P. acnes- mediated TLR activation is an important step in the complex natural history of the acne lesion." (PMID 24011352, 2013). "Oral probiotics can regulate the release of inflammatory cytokines within the skin, and a specific reduction in interleukin-1 alpha (IL-1-α), noted under certain experimental conditions, would certainly be of potential benefit in acne." (PMID 21281494, 2011). "IL-1R can be activated by IL-1α and IL-1β within the inflamed comedones of acne patients." (PMID 38731983, 2024). "has revealed prominent escalations in CD3+ and CD4+ T cells, macrophages, and IL-1α in the dermis surrounding unaltered hair follicles in individuals afflicted with acne, suggesting inflammation as a precursor to the manifestation of acne." (PMID 38550588, 2024). "IL-1α is highly expressed in sebaceous epithelial cells and hair follicles in patients with acne." (PMID 32627753, 2020).
acne (continued). "Interleukin (IL)-1α and IL-6 are predominant in the inflammatory lesions of acne vulgaris." (PMID 32627753, 2020). "There is much speculation regarding the source of infundibular IL-1α in acne, and there are reports of release either by keratinocytes or by the cells of the immune system." (PMID 24011352, 2013). "TLR activation and secretion of IL-1α from keratinocytes may be initiating steps in comedogenesis and, therefore, critical to the pathophysiology of acne." (PMID 24011352, 2013). "Thus, P. acnes triggers the secretion of IL-1α, TNF-α, and the chemokine IL-8 which have been implicated in the inflammatory process of acne." (PMID 19629174, 2009). "The obtained results show a nearly complete ablation in the formation of IL-1α, IL-8 and IL-6, which subsequently prevents the inflammatory cytokines from mediating innate and adaptive immunity and multiple physiological processes, thus preventing the onset of acne-induced skin inflammation." (PMID 36838382, 2023). "Similarly, only very small amounts of IL-1α were produced, whereas this cytokine has been reported to be produced in large amounts in keratinocytes in vitro and in a mouse model in vivo involving a sebum-like application of acne-related C. acnes strains." (PMID 35563458, 2022). "Therefore, inhibition of P. acnes-induced IL-6 and IL-1α expression could relieve the symptoms of acne." (PMID 32627753, 2020). "Evidences indicated that IL-1α is one of the main inflammatory factors, which could induce the proliferation of keratinocytes and sebaceous gland cells and eventually promote the formation of acne vulgaris." (PMID 33082712, 2020). "The present study is the first to evaluate the serum levels of IL-1α, IL-1β, IL-6, IL-8, IL-12β, IL-15, TNF-α, and granulocyte-macrophage colony-stimulating factor in acne subjects compared with the levels in healthy controls." (PMID 31951642, 2020). "Further studies are needed to explore the correlation between MMP-2 activity and expression of IL-1a and β, TNF-α, and triglycerides in acne." (PMID 31032338, 2019). "Moreover, IL-1α may contribute to both the creation of a comedogenic cytokine millieu, as well as promoting the eventual sebocyte hypercornification characteristic of acne lesions." (PMID 24011352, 2013). "Our study suggests that MMP-2 CT/TIMP-2 GG genotype may correspond to decreased activity of MMP-2, which may lead to the high expression of IL-1a and β, TNF-α, and triglycerides observed in acne patients." (PMID 31032338, 2019).
Alzheimer disease (26 papers, 2008 to 2024). A progressive, neurodegenerative disease characterized by loss of function and death of nerve cells in several areas of the brain leading to loss of cognitive function such as memory and language. "In humans, IL1A allelic polymorphism leading to increased levels of IL-1α is associated with susceptibility to Alzheimer’s disease in some ethnic groups, due to promotion and secretion of the amyloid precursor protein." (PMID 36613465, 2022). "Accumulated evidence has shown that IL-1α and IL-8 share the same pathway in the inflammatory response, and a combination of these two genes has contributed to an increased risk of Alzheimer’s disease (AD)." (PMID 34207646, 2021). "Genetic studies about cytokines, specifically IL-α, have shown its notable genetic polymorphism and have found that patients expressing the IL-1α gene have a 10 times greater risk in developing Alzheimer’s disease." (PMID 32054121, 2020). "This network contains the proinflammatory cytokine Il1a, previously associated with Alzheimer’s disease, development and plasticity, immune associated genes (Cd80, Cr2, Cd27, Dapp1) and chemokines (Ccl3, Ccl4, Ccl21)." (PMID 23742273, 2013). "It has been reported that IL1A (-889T) allele upregulates transcription of the gene and thus increases the level of the gene product in Alzheimer's disease as well as the plasma level of IL1B." (PMID 20565898, 2010). "IL-1α and IL-1β have been identified as potent pro-inflammatory cytokines in many neurodegenerative diseases such as Alzheimer’s disease, Parkinson’s disease or multiple sclerosis, and have been suggested to accelerate the progression of neurodegeneration." (PMID 32933002, 2020). "IL-1α induces neurotoxic reactive astrocytes (A1 astrocytes), which contribute to neuron and oligodendrocyte death in neurodegenerative diseases, such as Alzheimer’s disease, amyotrophic lateral sclerosis and multiple sclerosis." (PMID 29666403, 2018). "Animal models of Alzheimer's disease, such as the APP transgenic line Tg2567 carrying the Swedish mutation, also show enhanced levels for TNF-α, IL-1β, IL-1α, chemoattractant protein-1, COX-2 and complement component 1q." (PMID 18564425, 2008). "We showed that the IL1A -889 T/T and IL1B +3954 T/T genotypes mark increased risk for late-onset Alzheimer's disease (LOAD) in an Australian cohort." (PMID 18715507, 2008). "BBB disruption is caused by the secretion of pro-inflammatory mediators, such as IL-1α, IL-1β, IL-6, and TNF-α, due to an increase in microglia and astrocytes in Alzheimer’s disease." (PMID 35453602, 2022). "A1-like astrocytes were found to be induced by the cytokine trio Il-1α, TNF, and C1q secreted by microglia and were identified in post-mortem samples from patients suffering from Alzheimer's disease (AD), Parkinson's disease (PD), amyotrophic lateral sclerosis (ALS), and multiple sclerosis (MS)." (PMID 37153637, 2023). "In this regard, in APP/PS1 transgenic mice, a model of Alzheimer’s disease, chronic treatment with ciproxifan reduced both COX-1 and COX-2 activities, decreased the level of pro-inflammatory cytokines IL-1α, IL-1β, and IL-6, and increased the level of anti-inflammatory cytokine TGF-1β." (PMID 33918940, 2021).
gastric cancer (24 papers, 2011 to 2025). A primary or metastatic malignant neoplasm involving the stomach. "Less is known about the involvement of IL-1α in gastric cancer progression, however IL-1α expression is increased in H. pylori associated pathology and elevated IL-1α in gastric tumors has been associated with liver metastasis." (PMID 25528766, 2015). "In our studies, we assessed the association of IL1A polymorphism in –889 position with the risk of occurrence of inflammatory changes of the gastric mucosa and of the intestinal type gastric carcinoma in patients infected with H. pylori." (PMID 23995914, 2013). "IL-1α promotes angiogenesis and the proliferation of vascular endothelial cells in gastric carcinoma, particularly in children with H. pylori-induced inflammation." (PMID 39354365, 2024). "IL-1α secreted from lung and gastric cancer cell lines has been reported to promote macrophage infiltration." (PMID 37998338, 2023). "IL-1α functions as a promoter of angiogenesis and vascular endothelial cell proliferation in gastric carcinoma since it is closely related to H.-pylori-induced inflammation in children." (PMID 35884067, 2022). "In other studies of human gastric cancers, it was found that expression of mature IL-1α was significantly correlated with the liver metastatic potential and angiogenesis of gastric cancer." (PMID 33430381, 2021). "In conclusion, after infection by H. pylori, gastric cells secrete and transfer exosomes containing active MET to nearby immune cells, which in turn promote gastric cancer progression via IL-1α." (PMID 34062919, 2021). "Interleukin-1 alpha (IL-1α) plays an important role in tumorigenesis and angiogenesis of gastric cancer." (PMID 29344744, 2018). "IL-1α, one of the most potent inflammatory cytokines, is reported to increase gastric cancer metastasis." (PMID 29344744, 2018). "In an earlier study we demonstrated that enhancement of VEGF expression by IL-1α mediated through IL-1RI plays an important role in the metastatic and invasive behaviors of gastric cancer cells." (PMID 29344744, 2018). "Our results show that IL-RA inhibits angiogenesis through the IL-1α/VEGF pathway in gastric cancer cell lines." (PMID 29344744, 2018). "The IL-1RA downregulated the metastatic potential of gastric cancer through blockage of the IL-1α/VEGF signaling pathways." (PMID 29344744, 2018). "Comparing with the normal group, the signal densities of cytokines were upregulated in the MNNG-induced gastric cancer groups, including Activin A, Agrin, IL-1α (both P < 0.01), ICAM-1 (P < 0.001), and TIMP-1 (P < 0.05)." (PMID 28119756, 2016). "Anti-IL-1α or anti-IL-1 receptor antagonist might represent a novel targeted therapy in gastric cancer since it was shown that it might suppress malignant cell growth in a gastric cancer cell line." (PMID 35884067, 2022). "Thus, given all the evidence in gastric cancer, IL-1α seems to play a promoting role in gastric cancer progression." (PMID 33430381, 2021). "We then investigated whether IL-1α promotes VEGF secretion by human gastric cancer cells and human umbilical vein endothelial cells (HUVECs) and, if so, whether and how IL-1RA affects the proliferation, invasion, and angiogenesis of HUVECs." (PMID 29344744, 2018). "Similarly, previous studies have shown that liver metastasis of gastric cancer is regulated by IL-1α via the enhanced proliferation of cancer cells and the accelerated process of angiogenesis via enhanced tube formation by HUVECs." (PMID 29344744, 2018). "IL-1α has been shown to regulate VEGF expression in gastric cancer." (PMID 29344744, 2018). "Our recent study has also reported that human gastric cancer cells overexpressing NDRG1 induces enhanced expression of IL-1α through activation of JNK and AP-1 (Jun/Fos), resulted in promoted expression of angiogenesis-related factors and tumor angiogenesis accompanied by macrophage infiltration." (PMID 24924428, 2014).